CD47 (CD47 molecule)
Diseases named in the same sentence as CD47 in open-access papers (continued):
Sharing a sentence is not in itself a finding about the gene and the disease.
tumor (continued). "Analyses of phagocytosis of the tumor cells by macrophage revealed that afatinib and the anti‐CD47 antibody treatment each alone enhanced phagocytosis and that a stronger effect on phagocytosis was observed upon combined treatment with both reagents." (PMID 37541303, 2023). "In cancer therapy, recombinant soluble SIRPα can bind to CD47 on tumor cells and disrupt the CD47-SIRPα interaction on macrophages, inducing phagocytosis of tumor cells." (PMID 37111479, 2023). "Our data revealed that fusion HAC NVs had significantly higher affinity for PD‐L1 and CD47 on tumour cells than fusion WT NVs, which promoted the antitumour function of macrophages and T cells both in vitro and in vivo." (PMID 37974395, 2023). "The SAP first binds to CD47 on tumor cells followed by cleavage of the MMP-2 responsive peptide linker in the tumor immune microenvironment." (PMID 36937769, 2023). "Both anti PD-L1 and anti CD47 have been able to suppress Treg function and reduce Treg number in tumor and lymphatic organs in previous studies." (PMID 36774400, 2023). "Within the tumor micronevironment, a pre-clinical study in triple negative breast cancer (TNBC) found that after chemotherapy that there was an increase in CD73, CD47, and PD-L1 positive tumor cells." (PMID 37033953, 2023). "The CD47/signal-regulatory protein alpha (SIRPα) pathway is a critical innate macrophage checkpoint, as CD47 expression on tumour cells limits the phagocytic function of TAMs." (PMID 38136335, 2023). "This should assist with our understanding of CD47-involved cellular immune response and tumor development and should be useful for developing novel therapeutic strategies targeting CD47 in cancers." (PMID 37241964, 2023). "We next examined the role of EGF‐induced and c‐Src‐upregulated CD47 expression in tumorigenesis and tumor immune evasion in mice." (PMID 37541303, 2023). "In preclinical studies, inhibiting CD47-TSP-1 signaling has been shown to reduce tumor cell survival and invasion." (PMID 38188674, 2023). "CD8+ T cells per gram of tumor increased in anti-CD47 manner; almost every therapeutic group which received anti-CD47 in the therapeutic regimen showed a significant increase in CD8+ T cells compared to groups which didn't receive it." (PMID 36774400, 2023). "Using immunomodulators to enhance the activation of DC cells while silencing the expression of the CD47 molecule in tumor cells can further improve the anti-tumor immune response." (PMID 37063284, 2023). "CD47 and PD-1 target two major immune cell groups in tumor immunotherapy, with CD47 antibody mainly regulating macrophages and PD-1 antibody mainly regulating T lymphocytes." (PMID 37484024, 2023). "SIRPα-Fc was able to disrupt CD47/SIRPα interactions by blocking CD47 in tumor cells, redirecting macrophages to the tumor site and killing the tumor cells." (PMID 37993941, 2023). "The platform showed that the combined effect of prodrug vesicle-induced ICD and aCD47-mediated CD47 blockage boosts anti-tumor immunity of the ICD inducer." (PMID 37144580, 2023). "In this study, we investigated the effectiveness of a combination treatment using an anti-CD47 antibody and cordycepin to enhance tumor inhibition." (PMID 37138855, 2023). "CD47 upregulation, a mechanism that which cancer cell increases their "selfness" plays an important role in inhibiting tumor cells' phagocytosis by macrophages and dendritic cells (DCs)." (PMID 36774400, 2023). "In the context of ovarian cancer, Shu and colleagues devised a dual CAR-T platform capable of recognizing TAG72 and CD47 on the surface of tumor cells of interest." (PMID 38146364, 2023). "The frequency of CD47+ cells positively correlated with the frequency of EpCAM+ tumor cells within both spheroids and tumoroids." (PMID 37876933, 2023). "Knockdown of Cd47 significantly decreased tumor formation in the lungs of mice and prolonged overall survival." (PMID 36413402, 2023).
tumor (continued). "Tumor cells escape phagocytosis through high expression of CD47, which has been demonstrated in vitro and in vivo." (PMID 37484024, 2023). "CM was enriched with proteins such as calreticulin, which acted as an extracellular tumor suppressor by interacting with CD47." (PMID 36943734, 2023). "Chemo-attractants/receptors (including CCL5/CCR5, CCL27/CCR10 and CX3CL1/CX3CR1) and immunomodulation of chemokine axes (including HLA-G and CD47) are involved in controlling NK cell recruitment to the tumor." (PMID 37064113, 2023). "CD47 was identified as the main macrophage checkpoint, and blocking CD47 can make macrophages phagocytize tumor cells and produce therapeutic clearance." (PMID 36575242, 2023). "Consistently, the analysis of circulating tumor cells isolated from the blood of breast cancer patients revealed that CD47 expression identified a subpopulation of cells with the capability to generate tumor xenografts in mice." (PMID 37540301, 2023). "In this context, EVs obtained from HEK 293 cells transfected to express SIRPα can accumulate in the tumor niche, inhibiting tumor growth by enhancing the phagocytosis of CD47+ tumor cells and increasing the infiltrating Tc cells." (PMID 37175226, 2023). "A study found that in a syngeneic mouse model, sEVs carrying the surface membrane protein SIRPα were transported to tumor sites, disrupting the CD47-SIRPα interaction and increasing the ability of macrophages to engulf tumor cells." (PMID 38093355, 2023). "Interaction of CD47 on tumor cells with SIRPα on TAMs thus constitutes an innate immune checkpoint that interferes with the detection and phagocytosis of the former cells by the latter." (PMID 38162643, 2023). "In summary, CD47 expression levels, SIRPα expression levels, tumor-infiltrating immune cells, immune checkpoint expression levels, and TMB are potential biomarkers that can help predict response to CD47-targeted therapy." (PMID 38188674, 2023). "Anti-SIRPα antibodies that target CD47-SIRPα axis have been reported to show promise in promoting anti-tumor immunity." (PMID 38239430, 2023). "The expression of CD47 on tumor cells is currently considered to be an immune-tolerance mechanism, as it can inhibit professional phagocytes from contractile engulfment of tumor cells by interacting with SIRPα." (PMID 37291116, 2023). "Through the signal regulatory protein α/cluster of differentiation 47 (SIRPα/CD47) pathway, tumour escape from phagocytic clearance of macrophage." (PMID 37974395, 2023). "The synergistic effect of bispecific antibodies targeting CD47 and other tumor antigens can potentially increase the safety and efficacy of treatment by targeting tumor cells preferentially." (PMID 36726125, 2023). "Anti‐CD47‐PCM@NP exhibited substantial suppressions on tumor growth, realizing over 40% reduction of average tumor volume compared with the anti‐CD47 group." (PMID 36683161, 2023). "Currently the clinically most advanced agents targeting myeloid checkpoints block the interaction between CD47 on tumor cells and the signal regulatory protein alpha (SIRPα) expressed on myeloid cells." (PMID 37346044, 2023). "The number of ongoing clinical trials of CD47 and SIRPα antagonists is increasing as strong emerging evidence showed CD47/SIRPα axis blockage promotes tumor control." (PMID 36626230, 2023). "Firstly, suppression of the CD47-SIRPα interaction results in macrophage phagocytosis of tumor cells." (PMID 36726125, 2023). "These agents are designed to block the interaction between CD47 and SIRPα to relieve suppression of cancer cell phagocytosis by APCs in order to stimulate tumor immunity." (PMID 37958404, 2023). "Imiquimod, a TLR-7 agonist, and anti-CD47 antibodies were delivered together on a nanoscale metal framework, leading to tumor eradication when combined with checkpoint inhibitors in a colorectal tumor model." (PMID 37090720, 2023).
tumor (continued). "The third consideration would be to engineer differential affinity for the alternative non-CD47 targeted component of the bispecific, allowing for greater binding interactions which should reduce binding to off-tumor CD4729,30." (PMID 37012357, 2023). "This VV exerted potent anti-tumor activity in a mouse model of osteosarcoma and can be broadly applied to tumors expressing CD47." (PMID 37993941, 2023). "Since the successful introduction of checkpoint inhibitors targeting the adaptive immune system, monoclonal antibodies inhibiting CD47-SIRPα interaction have shown promise in enhancing anti-tumor treatment efficacy." (PMID 38138970, 2023). "Given the ubiquitous expression of CD47 on normal cells, tumor-specific delivery of CD47 blockade would generate better anti-tumor effects with fewer side effects than systemic administration." (PMID 37063284, 2023). "Anti-tumor efficacy of anti-CD47 therapy alone and in combination was investigated both in-vitro and in-vivo using cell-line derived xenograft (CDX) and patient-derived xenograft (PDX) models." (PMID 37468567, 2023). "Immune checkpoint molecules, such as PD-L1, CTLA-4 and CD47, are important regulators that induce tumour cell immune escape." (PMID 36902476, 2023). "On the other hand, the interaction of cancer cell CD47 with macrophage SIRPα inhibits phagocytosis to promote tumor progression." (PMID 36823443, 2023). "In vivo antitumor assay demonstrated the most prominent tumor inhibition effect of anti‐CD47‐PCM@NP/PTX which suppressed the tumor volume from ≈200 mm3 to ≈160 mm3, proving consistent tendency with in vitro IC50 results." (PMID 36683161, 2023). "Of note, combination of CD47-SIRPα interaction blockade with ionizing radiation (IR) synergistically inhibits tumor growth." (PMID 36882648, 2023). "The current paradigm regarding MOAs of CD47 targeting for cancer therapy is largely based on the tumor cell bearing CD47 targeting to block its binding to SIPRα ligand on macrophages and DCs13,14, which activate both anti-tumor innate and adaptive immunity." (PMID 37012357, 2023). "Knock‐in expression of CD47 Y288F reduced CD47 expression, increased phagocytosis of the tumor cells by macrophage, and reduced tumor growth." (PMID 37541303, 2023). "Results derived from tumor studies in the NOD strain of mice are further complicated by the fact that human CD47 binds to NOD-Sirpα with 10× greater affinity than to human SIRPα." (PMID 37958404, 2023). "Numerous studies have confirmed that CD47 is overexpressed in several tumor types, such as myeloma, breast cancer, leiomyosarcoma, and acute lymphocytic cancer." (PMID 36845095, 2023). "Immunohistochemical (IHC) analysis revealed that THCs, positive for macrophage F4/80 and epithelial pan-CK, were present in 1–2% of subcutaneous tumor after inoculating low CD47-expressing C4-2 cells into immunocompromised Nu/Nu mice." (PMID 37848444, 2023). "Its primary purpose is to engage with CD47, a self-recognition marker, to reduce professional phagocytes from engulfing self-cells, together with tumor cells." (PMID 37291116, 2023). "In summary, our results support a role for GPR183 in the recognition and elimination in vitro and in vivo of malignant B cells by activated macrophages, upon concomitant targeting of CD20, CD47 and PI3Kδ in tumor cells." (PMID 37153563, 2023). "CBD-SIRPαFc derived collagen affinity and showed faster accumulation and prolonged retention in tumor than unmodified SIRPαFc, providing a possible strategy to avoid off-target adverse reactions in anti-CD47 therapy." (PMID 37692860, 2023). "Currently, by blocking CD47-signal regulatory protein α (SIRPα) signaling, restoring phagocytosis of tumor cells by macrophages, and promoting the response of effector CD8+ T cells, tumor cell proliferation and metastasis are effectively inhibited." (PMID 37055849, 2023). "OXP combined with anti-CD47, and anti-PD-L1 increased survival of mice and reduced tumor growth compared to OXP alone." (PMID 36774400, 2023).
tumor (continued). "Preclinical studies have demonstrated that CD47 blockade enhances the phagocytosis of cancer cells by macrophages and promote anti-tumor immune responses." (PMID 38188674, 2023). "Bispecific antibodies have been engineered with one Fab fragment targeting CD47 and the other with high affinity for a tumor-specific antigen, enabling them to recognize two different molecules simultaneously." (PMID 37958404, 2023). "Tumor bioluminescence was lower in mice in which CD47 was blocked with B6H12 or 5-Fu (*P < 0.05, **P < 0.01) than in IgG-treated (control) mice." (PMID 36860925, 2023). "Raji tumor cells express pro-phagocytic molecules such as calreticulin together with CD47, and the interaction of hCD47 on Raji cells with hSIRPα on human macrophages likely inhibits phagocytosis of tumor cells." (PMID 38162643, 2023). "Tumor cells expressing membrane protein CD47 bind to SIRPα on the surface of TAM, which transmits “don’t eat me” signals to macrophages through downstream signaling pathways and inhibits the phagocytic ability of macrophages." (PMID 37810971, 2023). "It has been proved that QPCTL inhibitors can block the recognition effect of CD47 on SIRPα and restore phagocytic function of macrophages, and enhance the anti-tumor effect in vivo." (PMID 37484024, 2023). "Studies in syngeneic cancer models have shown that CD47 mAbs can effectively inhibit tumor growth and that efficacy is dependent on macrophages, dendritic cells, T cells, and their interactions." (PMID 37958404, 2023). "Of importance, CD47 expression and, therefore, immune evasion in ovarian CSCs has been shown to be induced by surrounding bulk tumor cells." (PMID 36900399, 2023). "When PD‐L1 and CD47 are both over expressed on tumour cells, PD‐L1 sends a ‘don't find me’ signal to the adaptive immune system and CD47 sends a ‘don't eat me’ signal to the innate immune system." (PMID 37974395, 2023). "Recently, disruption of the disialoganglioside GD2/Siglec-7 axis with a GD2 antibody in combination with a CD47 antibody resulted in tumor eradication in syngeneic and xenograft mouse models of neuroblastoma by recruitment of macrophages." (PMID 37346044, 2023). "RGD endowed HENPs with tumor-targeting capacity, while CD47 helped to evade phagocytosis from the mononuclear phagocyte system (MPS)." (PMID 37717008, 2023). "RAGA knockdown increases CD47 protein level, thereby prevents the engulfing of cancer cells by macrophages and promotes tumor growth." (PMID 36823443, 2023). "The activity of macrophages on tumor cells is controlled through the interaction of tumoral CD47 with its receptor in macrophages, signal regulatory protein a (SIRPα)." (PMID 37199012, 2023). "Although CD47 is abundantly expressed in erythrocytes and platelets, tumor cells also express CD47 to prevent phagocytosis by macrophages." (PMID 37892225, 2023). "Most studies investigating CD47 blockade in tumor models have attributed its anti-tumor effects to enhanced phagocytosis and adaptive tumor immunity mediated by APCs and CD8 T cells." (PMID 37958404, 2023). "This suggests that tumor cells expressing CD47 can avoid macrophage phagocytosis, allowing them to escape being cleared by macrophages." (PMID 37484024, 2023). "Tumor cells can effectively evade immune surveillance and clearance mechanisms by overexpressing CD47." (PMID 37484024, 2023). "Here the authors describe the design of alternating magnetic field-manipulated bacteria engineered to release an anti-CD47 nanobody, promoting anti-tumor immune response in preclinical cancer models." (PMID 36959204, 2023). "The “don’t eat me” signal CD47-SIRPα axis is a well-liked target in the development of anti-tumor therapeutics." (PMID 37345054, 2023). "Preclinical tumor models have demonstrated that the abrogation of the CD47/signal regulatory protein alpha (SIRPα) axis is sufficient to trigger DC/NK cell crosstalk." (PMID 37298470, 2023).
tumor (continued). "In phagocytic synapse (right side), the binding of signaling regulatory protein alpha (SIRPα) on macrophage to CD47 on AML (or other tumor cell) results in inhibition of phagocytosis." (PMID 37020553, 2023). "For this reason, an improved understanding and consideration of the signaling axes disrupted by CD47 blockade in tumor, immune, and other stromal cells is required to fully interpret its anti-tumor efficacy." (PMID 37958404, 2023). "Due to the binding of tumoral CD47-exosomal SIRPα, macrophages cannot recognize tumoral CD47 “don’t eat me” signals and phagocytose more tumour cells." (PMID 37461033, 2023). "It is necessary to summarize the treatment of CD47 in non-tumor diseases, and explore what kind of inspiration can be obtained from tumor treatment and how to avoid problems in tumor treatment." (PMID 38125492, 2023). "Studies in preclinical NSCLC models have demonstrated that inhibition of CD47 using genetic or pharmacologic approaches impairs malignant phenotypes including tumor growth and immune escape, metastasis, stemness, and drug resistance." (PMID 37958404, 2023). "Alongside T cells, macrophages have emerged as major mediators of the anti-GPC2 ADC treatment, and the combination of anti-GPC2 ADCs with anti-CD47 blockade has demonstrated a modest reduction in tumor burden." (PMID 38087370, 2023). "The interaction of CD47 and SIRPα on macrophages can aid the tumor cells to escape the phagocytic clearance of macrophages, though blocking CD47 can reverse macrophage-mediated tumor inhibition." (PMID 36792608, 2023). "Below, we report the findings of studies identified using the PubMed search “lung AND (cancer OR tumor OR tumour) and (CD47 or SIRPα)”." (PMID 37958404, 2023). "Tumoral cells often upregulate "Don't eat me" signals like CD47, programmed cell death ligand 1 (PD-L1), and B2M." (PMID 37822610, 2023). "The CD47-SIRPA interaction between tumor cells and myeloid cells is critical to phagocytosis blockage and immune escape, which further supports the immunosuppressive role of MRS2 cells in HCC." (PMID 36937389, 2023). "When mice with B16vIII tumors were coadministered with P/Tr/Td-fibers and anti-PD-L1 and anti-CD47 there was significant tumor inhibition and long-term survival compared to the blockade group and the P/Tr/Td-fiber alone." (PMID 36937769, 2023). "CD47 plays an important role in the immune evasion of tumor cells through direct or indirect interactions with different types of immune cells." (PMID 36598153, 2023). "We observed that the highest infiltration with CD47 positive (CD47+) tumor cells was in the tumor periphery of AdCaNOS." (PMID 36171566, 2022). "The phase I clinical trial of HU5F9-G4 indicates that enhancement of macrophage phagocytosis by blocking CD47 is a promising approach for tumor therapy." (PMID 35672862, 2022). "This concept has been described for bsAbs targeting tumor-specific receptors with high affinity on one arm and CD47 with lower affinity on the other arm." (PMID 35479092, 2022). "CD47, also known as integrin-associated protein (IAP) or Antigenic surface determinant protein OA3, is a glycoprotein with an immunoglobulin-like structure that is widely expressed in tumor cells." (PMID 36558902, 2022). "Bifidobacteria promote local anti-CD47 to tumor immunotherapy by accumulating in the TME, which effectively stimulates the stimulator of interferon genes signaling and increases the cross-initiation of dendritic cells (DCs) after anti-CD47 treatment." (PMID 36438840, 2022). "Another target that is being evaluated for tumour‐directed CD47 blocking is CD70, with CD70 antibodies themselves already being pursued for the treatment of solid cancers." (PMID 35908284, 2022). "(ii) Safety: blocking the interaction between CD47 and the signal-regulating protein α (SIRPα) expressed on phagocytes can promote phagocytosis of phagocytes against tumor cells." (PMID 35832081, 2022).